APOM (apolipoprotein M)
Diseases named in the same sentence as APOM in open-access papers (continued):
Sharing a sentence is not in itself a finding about the gene and the disease.
pancreatic cancer (1 paper, 2023). "The mRNA expression levels of CSTF2, FAF2, KIF20B, AKR1A1, APOM, KRT6C, and CD70, which were included in the prognostic model, were detected in different types of pancreatic cancer cell lines." (PMID 38268915, 2023). "Indeed, there are extremely few high-quality mechanistic studies on other signature genes (e.g., CSTF2, APOM, and KRT6C) that may serve as targets for subsequent studies on the molecular mechanisms of pancreatic cancer." (PMID 38268915, 2023).
spina bifida (1 paper, 2025). A congenital neural tube defect in which vertebrae are not fully formed. "Third, we only used human fetuses with spina bifida at 24–33 weeks of pregnancy to verify ApoM expression." (PMID 39827160, 2025).
vocal cord polyp (1 paper, 2020). "In the present study, we first found that the APOM protein level in LC tissues was significantly lower than that in paracarcinomatous tissues and vocal cord polyp tissues." (PMID 33173129, 2020). "The results of western blot based on capillary electrophoresis technology showed that the APOM protein level in cancer tissues was lower than that in paracarcinomatous tissues (P = 0.0003) and in vocal cord polyp tissues (P < 0.0001)." (PMID 33173129, 2020).
tumor (16 papers, 2010 to 2025). "Since S1P inhibits the invasion of several tumor cells, apoM could be associated with certain types of cancer via S1P, which may be a novel line of research in future." (PMID 32306242, 2020). "S1PR1 has been reported to be upregulated by ApoM overexpression, which promotes proliferation and invasion in vitro as well as tumor growth in vivo in the A549 cell line." (PMID 39551792, 2024). "In contrast, a study investigating the effect of APOM on CRC cell proliferation and apoptosis found that the upregulation of APOM was associated with lower apoptosis rates and higher tumor growth in Caco-2 cells." (PMID 38067270, 2023). "At the end of 0, 4, 8, 12, 16, and 20 weeks, the mice were killed and the livers were taken to determine the ApoM gene pair and the effect of tumor formation rate in C57BL/6J mice." (PMID 34149930, 2021). "Significantly different from the control group, the ApoM gene deletion group had a faster tumor growth rate, and we found that the difference between the two appeared on the 16th day after subcutaneous injection." (PMID 34149930, 2021). "APOM was recently reported to be protective against tissue injury and fibrosis in the kidney, liver, and lung, endotoxin-induced inflammation, and tumor development, suggesting that APOM changes could contribute to KO mice phenotype." (PMID 39969482, 2025). "In contrast to previous studies, a recent study by Zhu and colleagues reported that the upregulation of APOM stimulates cell proliferation, invasion, and tumor development in NSCLC by inducing sphingosine-1-phosphate, leading to the activation of the ERK1/2 and PI3K/AKT signaling pathways." (PMID 38067270, 2023). "Moreover, RPS27A expression was remarkably higher in CRC tissues in contrast with the tumor-adjacent tissues and was positively correlated with the ApoM level in tumor tissues, and higher RPS27A expression was associated with smaller tumors and lower T stage." (PMID 33564284, 2021). "After tumor mutation profile and copy number variation (CNV) analyses, we established and validated a prediction model of KRAS mutations, based on survival analysis and mRNA expression, that contained seven genes: CSTF2, FAF2, KIF20B, AKR1A1, APOM, KRT6C, and CD70." (PMID 38268915, 2023). "Therefore, APOM could potentially play a role in a tumor-suppressing mechanism, yet this requires further studying." (PMID 38067270, 2023). "Different from ApoA1 and ApoM, a high ApoB level may be a risk factor for HCC as it is correlated with poorer post-surgery survival in HCC patients, and individuals with higher ApoB level tend to have a larger tumor size." (PMID 36506554, 2022). "Moreover other researches indicated that apoM might be also involved in the immunity, inflammation, and neoplasia." (PMID 22054074, 2011). "APOM and SOD2 are involved in antioxidant defense, helping tumor cells survive in highly oxidative conditions." (PMID 40989695, 2025). "Proteins in HLH cluster, implying the recovery of tumor-inhibited protein expression after the DBT, participated in lipid binding and antioxidant activity (APOM, CETP, and ALB)." (PMID 38719824, 2024). "The authors further investigated the potential role of APOM in regulating the epithelial–mesenchymal transition (EMT), a process involved in tumor invasion and metastasis." (PMID 38067270, 2023). "Through S1P/S1PR1 signaling, ApoM activates the downstream signaling pathways including ERK1/2 and PI3K/AKT pathways, which promote cancer cell proliferation and invasion in vitro and tumor growth in vivo." (PMID 36506554, 2022). "There was higher expression of APOM in NSCLC tissues than in non‐NSCLS and of APOM overexpression promoted invasion and proliferation of NSCLC cells in vitro and tumor growth in vivo by upregulating expression of S1PR1 and activating the PI3K/AKT and ERK1/2 signaling pathways." (PMID 31573738, 2019).
cancer (15 papers, 2010 to 2024). A tumor composed of atypical neoplastic, often pleomorphic cells that invade other tissues. "For example, ApoC1 is found to promote breast tumorigenesis by altering cell adhesion and migration processes, while ApoM has inhibitory effects on cancer cell invasion and proliferation, potentially by its interaction with vitamin D receptors." (PMID 39744067, 2024). "The APOM has been identified as a protective factor against the occurrence and progression of various cancers, exhibiting inhibitory actions on cancer cell proliferation, migration, and invasion." (PMID 39175755, 2024). "ApoM is downregulated in BC tissues and can hamper the proliferation and invasion of the cancer cells, possibly by upregulating the expression of vitamin D receptors (VDRs)." (PMID 36506554, 2022). "Further support for this theory can be found—in an analysis of 50 matched primary liver tumours and adjacent matched normal tissue, ApoM was lower in the cancer liver tissue samples." (PMID 35158806, 2022). "The expression level of the ApoM gene in the cancer tissues was lower than that in paracarcinoma tissues." (PMID 34149930, 2021). "The expression level of ApoM in cancer tissues of WT mice was significantly lower than that of paracarcinoma tissues." (PMID 34149930, 2021). "The Cancer Genome Atlas (TCGA) database and clinical case analysis, as well as animal level and cell level analysis suggest that the expression level of ApoM gene in cancer tissues is lower than that in paracarcinoma tissues." (PMID 34149930, 2021). "When making comparisons to normal or benign colorectal tissues, the levels of apoM mRNA and protein are decreased in cancer tissues." (PMID 32306242, 2020). "Prior studies have shown that apolipoprotein M (APOM) is involved in the development of some cancers." (PMID 33173129, 2020). "And apoM protein mass was also much lower in the cancer tissues than those in the polyp tissues, normal mucosa and inflammatory mucosa." (PMID 20846402, 2010). "In parallel the apoM immunohistochemical staining were also much weaker in the cancer tissues than in their adjacent normal tissues (P < 0.0001)." (PMID 20846402, 2010). "A study shows that ApoM may inhibit CRC development, while another study suggests that the high expression of ApoM in CRC cells promotes cancer cell proliferation and suppressed apoptosis via increasing the expression of ribosomal protein S27A (RPS27A)." (PMID 36506554, 2022). "In addition, the level of apoptosis in cancer tissues of WT mice was higher than that of ApoM-/- mouse cancer tissues." (PMID 34149930, 2021). "Our previous studies have shown that APOM is also involved in the development of several cancers." (PMID 33173129, 2020). "Certainly it needs a standardized method for determining apoM mRNA level in the cancer tissues." (PMID 20846402, 2010). "We suspected whether apoM expression in adult colorectal tissues was influenced under cancer condition." (PMID 20846402, 2010). "The significance of this finding is due to the role of APOM as a primary carrier for sphingosine-1-phosphate, which is a signaling molecule responsible for inhibiting ceramide; the inhibition of ceramide leads to suppressed apoptosis and increased cell proliferation, leading to cancer." (PMID 38067270, 2023). "According to a recent publication, several proteins, including ABCA1, APOA1, APOE, apolipoprotein M (APOM), and SRB1, are involved in the influx and efflux of lipids in cancer cells." (PMID 37375802, 2023). "While the roles of specific APOs like APOC2, APOD, and APOM are still under investigation, continued research promises to deepen our understanding of how the APO family interacts with cancer." (PMID 38067270, 2023).
cardiovascular disease (12 papers, 2013 to 2025). "SLE patients have increased cardiovascular disease risk, and we aimed to investigate if apoM levels reflect endothelial function in SLE." (PMID 31046824, 2019). "High-density lipoprotein (HDL)-bound apolipoprotein M/sphingosine 1-phosphate (ApoM/S1P) complex in cardiovascular diseases serves as a bridge between HDL and endothelial cells, maintaining a healthy endothelial barrier." (PMID 36430543, 2022). "Drugs targeting the S1P-receptor pathways are evolving as well as apoM-modulating drugs with a focus on cardiovascular diseases and inflammation; however, only a few of these studies have also reported data that are relevant to kidney biology." (PMID 34722589, 2021). "Further studies are needed to investigate the predictive value of apoM in the development of a cardiovascular disease." (PMID 31046824, 2019). "S1P is mostly bound to apolipoprotein M (ApoM, 50–70%) and albumin (ca. 30%), and recent reports point to an important role of HDL-bound S1P, especially in context of protection against cardiovascular disorders." (PMID 32759843, 2020). "We found 6 proteins that mediated the PGSCAD’s effect on MACE in EXSCEL (C9, LBP, ITIH4, APOM, CES1, and HS6ST2), providing supporting evidence that they might serve as biomarkers for cardiovascular disease in patients with T2D52–54." (PMID 40032831, 2025).
kidney disease (8 papers, 2019 to 2025). "Altogether, the data available points toward a complex biology where the association of both apoM and S1P with kidney disease varies, likely depending on the underlying etiology of the disease." (PMID 34722589, 2021). "However, accumulating data suggest that apoM is not only affected by kidney disease, but also has a causal role." (PMID 34722589, 2021). "In summary, the current studies provide evidence that support a role for the apoM/S1P axis in kidney disease; however, additional pre-clinical and clinical studies are needed to reveal the mechanisms and target potential in the treatment of patients." (PMID 34722589, 2021). "In this review, we present what has so far been elucidated about the role of apoM in normal kidney biology and describe how changes in the apoM/S1P axis are thought to affect the development of kidney disease." (PMID 34722589, 2021). "This highlights the complexity of kidney diseases in general and the possible role of apoM and S1P in the development of kidney disease and needs to be included in the interpretation of apoM and/or S1P as biomarkers for kidney disease in future studies." (PMID 34722589, 2021). "Studies of patients or animals with kidney disease and effects on apoM levels." (PMID 34722589, 2021). "The increasing knowledge from other studies related to different organs or diseases suggests that apoM might also play a role in the pathology of kidney disease." (PMID 34722589, 2021). "Furthermore, induction of mild kidney disease by 5/6-nephrectomy in mice resulted in a somewhat surprising increase in plasma apoM levels." (PMID 34722589, 2021). "The discrepancies found for the association of apoM and kidney function in the different studies may, to some extent, reflect that the underlying etiology for developing CKD is very diverse and that conditions other than kidney disease itself are more important for determining apoM levels." (PMID 34722589, 2021). "Thus, the apoM levels observed in this study may be explained by the cholesterol levels and not the kidney disease, again supporting the idea that circumstances other than kidney disease itself determine apoM levels in patients with CKD." (PMID 34722589, 2021).
infection (7 papers, 2012 to 2022). The state of being infected such as from the introduction of a foreign agent such as serum, vaccine, antigenic substance or organism. "In contrast, serum amyloid A4-protein and apolipoprotein M were down-regulated on day-56 post-infection." (PMID 36227939, 2022). "To determine the possible relation between serum levels of S1P and apoM and the severity of infection in COVID‐19 patients, we used PSI, length of hospitalization, and NLR as parameters." (PMID 33190411, 2021). "In the same context, apolipoprotein M (ApoM), a cardioprotective apolipoprotein, is a negative acute response protein, levels of which decrease in response to inflammation and infection." (PMID 35350538, 2022). "Data from humans and mice demonstrate that apoM is a negative acute phase response protein with decreased mRNA and circulating protein levels during infection and inflammation." (PMID 31046824, 2019). "ApoM levels in the patient group with infections without SIRS were also significantly lower than apoM levels in controls." (PMID 22512779, 2012). "The group with SIRS without infection also demonstrated very low apoM levels." (PMID 22512779, 2012). "ApoM is a negative acute-phase protein that decreases during infection and inflammation." (PMID 22512779, 2012).
metabolic disease (4 papers, 2013 to 2026). A congenital disorder (due to inherited enzyme abnormality) or acquired (due to failure of a metabolically important organ) disorder resulting from an abnormal metabolic process. "But the effects of S1P associated with apoM in metabolic disease are still unknown." (PMID 23360427, 2013). "Advancing ApoM-based therapies may offer a novel precision medicine strategy to treat cardiovascular and metabolic diseases through endothelial-targeted modulation of S1P signaling." (PMID 41771322, 2026). "Taken together, these observations indicate that APOM might be beneficial in the field of cardiac and metabolic diseases." (PMID 34638803, 2021). "Animal studies provide further insight into the role of APOM in metabolic diseases." (PMID 34638803, 2021). "Therefore, the APOM/S1P complex as well as free APOM might be interesting targets in the metabolic diseases research area." (PMID 34638803, 2021).
immune diseases (2 papers, 2019 to 2024). "We proposed that apoM-S1P may play a role in resisting inflammation and immune dysfunction in lgAV patients." (PMID 31885732, 2019).
kidney (1 paper, 2024). "The increased apoM levels do, however, not protect against acute kidney injury." (PMID 38313311, 2024).
neurological diseases (1 paper, 2020). "Thus, changes in APOD and APOM levels could contribute to the association of the PON1 genotype with cardiovascular and neurological diseases." (PMID 33260536, 2020).
APOM also shares sentences with these, for which no sentence is quoted: Hypercholesterolemia (4 papers); colorectal adenocarcinoma (2); larynx carcinoma (2); lung carcinoma (2); retinal disorder (2); allergic rhinitis (1); Angina (1); brain infarct (1); Cardiac Diseases (1); cardiac hypertrophy (1); cholangitis (1); chronic heart failure (1); chronic hepatitis (1); dementia with (1); dengue fever (1); end-stage renal disease (1); esophageal cancer (1); gestational diabetes (1); glomerulopathies (1); Glucose intolerance (1); IgA Vasculitis (1); Impaired glucose tolerance (1); inflammation (1); ischemia (1); Liver Fibrosis (1); lupus nephritis (1); nephrotic syndrome (1); neuropathy (1); Parkinson disease (1); peripheral arterial disease (1).
A further 7 diseases each share a sentence with APOM in 1 paper.